RAB8A (RAB8A, member RAS oncogene family)
Description:
The small GTPases Rab are key regulators of intracellular membrane trafficking, from the formation of transport vesicles to their fusion with membranes. Rabs cycle between an inactive GDP-bound form and an active GTP-bound form that is able to recruit to membranes different sets of downstream effectors directly responsible for vesicle formation, movement, tethering and fusion. RAB8A is involved in polarized vesicular trafficking and neurotransmitter release. Together with RAB11A, RAB3IP, the exocyst complex, PARD3, PRKCI, ANXA2, CDC42 and DNMBP promotes transcytosis of PODXL to the apical membrane initiation sites (AMIS), apical surface formation and lumenogenesis. Regulates the compacted morphology of the Golgi. Together with MYO5B and RAB11A participates in epithelial cell polarization. Also involved in membrane trafficking to the cilium and ciliogenesis. Together with MICALL2, may also regulate adherens junction assembly (By similarity). May play a role in insulin-induced transport to the plasma membrane of the glucose transporter GLUT4 and therefore play a role in glucose homeostasis (By similarity). Involved in autophagy. Participates in the export of a subset of neosynthesized proteins through a Rab8-Rab10-Rab11-dependent endososomal export route. Targeted to and stabilized on stressed lysosomes through LRRK2 phosphorylation. Suppresses stress-induced lysosomal enlargement through EHBP1 and EHNP1L1 effector proteins.
Synonyms: MEL; RAB8
Tractability: Small molecule: a structure with a bound ligand is known. Antibody: UniProt places it where antibodies can reach, with high confidence; its Gene Ontology location is reachable by antibodies, with high confidence; the Human Protein Atlas places it where antibodies can reach. PROTAC: ubiquitination databases record sites on it; its protein half-life has been measured.
Target class: Enzyme; Hydrolase
Gene: Protein-coding gene on chromosome 19 (16,111,843 to 16,134,234, forward strand). Ensembl gene ENSG00000167461.
Subcellular location: Cell membrane; Golgi apparatus; Endosome membrane; Recycling endosome membrane; Cell projection, cilium; Cytoplasmic vesicle, phagosome; Cytoplasmic vesicle, phagosome membrane; Cytoplasm, cytoskeleton, microtubule organizing center, centrosome, centriole; Cytoplasm, cytoskeleton, cilium basal body; Midbody; Cytoplasm, cytoskeleton, cilium axoneme; Cytoplasm; Lysosome
Subcellular location (Human Protein Atlas): Nucleoli; Nucleoplasm; Plasma membrane; Basal body; Centriolar satellite; Cytosol; Golgi apparatus; Primary cilium
Pathways (Reactome):
Vesicle-mediated transport: RAB GEFs exchange GTP for GDP on RABs; TBC/RABGAPs; Translocation of SLC2A4 (GLUT4) to the plasma membrane
Organelle biogenesis and maintenance: Anchoring of the basal body to the plasma membrane; VxPx cargo-targeting to cilium
Cell Cycle: Regulation of PLK1 Activity at G2/M Transition
Metabolism of proteins: RAB geranylgeranylation
Gene Ontology:
Molecular function: G protein activity; GDP binding; GTP binding; GTPase activity; myosin V binding; protein binding; small GTPase binding; protein kinase binding; protein tyrosine kinase binding
Biological process: cilium assembly; Golgi organization; Golgi vesicle fusion to target membrane; regulation of autophagy; axonogenesis; cellular response to insulin stimulus; endocytic recycling; exocytosis; neurotransmitter receptor transport to postsynaptic membrane; protein localization to cilium; protein localization to plasma membrane; neurotransmitter receptor transport, endosome to postsynaptic membrane; regulation of long-term neuronal synaptic plasticity; regulation of protein localization; regulation of protein transport
Cellular component: centrosome; cilium; cytoplasm; endosome membrane; extracellular exosome; Golgi apparatus; midbody; non-motile cilium; phagocytic vesicle; plasma membrane; recycling endosome membrane; ciliary basal body; cytosol; endosome; Golgi membrane; synaptic vesicle; trans-Golgi network membrane; trans-Golgi network transport vesicle; axoneme; centriole; ciliary base; ciliary membrane; cytoplasmic vesicle; dendrite; glutamatergic synapse; and 5 more
Genetic constraint (gnomAD): Loss-of-function variants: 4 observed, 26.89 expected, observed/expected ratio (o/e) 0.15, 90% interval 0.072 to 0.34. The upper end of that interval is the gene's LOEUF score, 0.34, which puts it in group 1 of 6, group 1 being the genes least tolerant of losing a copy. Missense variants: 156 observed, 255.41 expected, observed/expected ratio (o/e) 0.61, 90% interval 0.54 to 0.7. Synonymous variants: 105 observed, 95.42 expected, observed/expected ratio (o/e) 1.1, 90% interval 0.94 to 1.29.
Homologues: Orthologues: macaque RAB8A (100% identical), chimpanzee RAB8A (99% identical), guinea pig RAB8A (98% identical), mouse Rab8a (97% identical), rat Rab8a (97% identical), tropical clawed frog rab8a (96% identical), zebrafish rab8a (93% identical), pig RAB8A (89% identical), dog RAB8A (85% identical). Paralogues in human: RAB8B (84% identical), RAB10 (68% identical), RAB13 (60% identical), RAB1A (53% identical), RAB1B (52% identical), RAB3A (50% identical), RAB3C (50% identical), RAB26 (48% identical), RAB3B (47% identical), RAB37 (47% identical), RAB3D (47% identical), RAB35 (46% identical), and 56 more.